IDH3A (isocitrate dehydrogenase (NAD(+)) 3 catalytic subunit alpha)
Description:
Catalytic subunit of the enzyme which catalyzes the decarboxylation of isocitrate (ICT) into alpha-ketoglutarate. The heterodimer composed of the alpha (IDH3A) and beta (IDH3B) subunits and the heterodimer composed of the alpha (IDH3A) and gamma (IDH3G) subunits, have considerable basal activity but the full activity of the heterotetramer (containing two subunits of IDH3A, one of IDH3B and one of IDH3G) requires the assembly and cooperative function of both heterodimers.
Synonyms: RP90
Tractability: Small molecule: a structure with a bound ligand is known. PROTAC: ubiquitination databases record sites on it; its protein half-life has been measured.
Target class: Enzyme; Oxidoreductase
Gene: Protein-coding gene on chromosome 15 (78,131,498 to 78,171,945, forward strand). Ensembl gene ENSG00000166411.
Subcellular location: Mitochondrion
Subcellular location (Human Protein Atlas): Mitochondria
Pathways (Reactome):
Metabolism: Citric acid cycle (TCA cycle)
Metabolism of proteins: Mitochondrial protein degradation
Gene Ontology:
Molecular function: isocitrate dehydrogenase (NAD+) activity; magnesium ion binding; protein binding; NAD binding; oxidoreductase activity, acting on the CH-OH group of donors, NAD or NADP as acceptor
Biological process: tricarboxylic acid cycle; carbohydrate metabolic process
Cellular component: isocitrate dehydrogenase complex (NAD+); mitochondrion; nucleus; mitochondrial matrix
Genetic constraint (gnomAD): Loss-of-function variants: 12 observed, 17.83 expected, observed/expected ratio (o/e) 0.67, 90% interval 0.43 to 1.09. The upper end of that interval is the gene's LOEUF score, 1.09, which puts it in group 4 of 6, group 1 being the genes least tolerant of losing a copy. Missense variants: 195 observed, 271.43 expected, observed/expected ratio (o/e) 0.72, 90% interval 0.64 to 0.81. Synonymous variants: 106 observed, 103.39 expected, observed/expected ratio (o/e) 1.03, 90% interval 0.88 to 1.21.
Homologues: Orthologues: macaque IDH3A (99% identical), pig IDH3A (98% identical), chimpanzee IDH3A (98% identical), dog IDH3A (98% identical), mouse Idh3a (98% identical), rat Idh3a (98% identical), guinea pig IDH3A (96% identical), rabbit IDH3A (93% identical), tropical clawed frog idh3a (85% identical), zebrafish idh3a (84% identical), Caenorhabditis elegans idha-1 (67% identical), Drosophila melanogaster Idh3a (67% identical), and 1 more. Paralogues in human: IDH3G (43% identical), IDH3B (42% identical).